TOP1 (DNA topoisomerase I)
Diseases named in the same sentence as TOP1 in open-access papers (continued):
Sharing a sentence is not in itself a finding about the gene and the disease.
colon cancer (continued). "Moreover, the obtained result lends further credence to the notion that the CPT sensitivity of colon cancer cells is highly influenced by the intracellular CKII activity and that this effect at least partly can be explained by altered TOP1 activity." (PMID 32423158, 2020). "In colon cancer, TDP1 depletion increased the sensitivity to irinotecan in a TOP1-dependent manner." (PMID 32028591, 2020). "Herein, we utilized the colon cancer cell lines, Caco2 and DLD1, to investigate heterogeneity of topoisomerase 1 (TOP1) activity in different cell subpopulations, and the consequences for the chemotherapeutic response towards the TOP1 targeting drug, camptothecin." (PMID 32423158, 2020). "Moreover, our finding that alterations in DoG RNA production in colon cancer are likely to have clinical relevance is further supported by our data revealing that DoG RNAs are induced in colon cancer in response to chemotherapeutic TOP1 poison CPT and TOP1 depletion." (PMID 38959318, 2024). "However, we previously demonstrated a direct correlation between TOP1 activity and the cellular drug response in various subpopulations of colon cancer cells that did not vary significantly with regard to TOP1 expression." (PMID 31783818, 2019). "Moreover, the differential CPT response of CSC-like versus non-CSC-like colon cancer cells may at least in part be ascribed to different intracellular CKII activity levels, which in turn affect TOP1 activity levels." (PMID 32423158, 2020).
melanoma (17 papers, 2012 to 2025). A malignant, usually aggressive tumor composed of atypical, neoplastic melanocytes. "These include two separate samples with mutation at W736 residue of Top1 (W736C), one malignant melanoma and the other urinary tract carcinoma, with 1.125% and 1.544% mutations at G4, respectively." (PMID 41009588, 2025). "In correlation with patient data and above results, the TOP1 inhibitor‐based targeted therapy showed that WRN‐deficient melanoma tumors were highly sensitive to TOP1 inhibition in preclinical in vivo mouse model." (PMID 35582959, 2022). "Among upregulated transcripts there was DNA topoisomerase I (TOP1), which is known to be associated with aggressive, advanced tumors and poor prognosis in melanoma." (PMID 32709086, 2020). "Among the upregulated genes were TOP1 (DNA topoisomerase I), which is associated with advanced melanomas and poor prognosis." (PMID 23056502, 2012). "Finally, we assessed therapeutic potential of TOP1 inhibitor for targeting WRN‐deficient melanoma tumor, which otherwise is known to be resistant to other therapeutic modalities." (PMID 35582959, 2022). "In addition, TOP1 amplification was reported to be associated with more advanced and poor prognostic tumors in melanoma." (PMID 32493317, 2020). "TOP1 is highly expressed in malignant tumors, including carcinomas of the colon, prostate, ovary, lung, and melanoma." (PMID 35055101, 2022). "We first applied the γH2AX/CC3(bleb) assay to examine the induction of DNA damage response and apoptosis pathways following treatment with the genotoxic DNA topoisomerase I inhibitor topotecan in the A375 melanoma xenograft model." (PMID 29682208, 2018). "In this line, it has been demonstrated that topoisomerase I (Top-1) inhibitor irinotecan (MM-398) is able to increase the sensitivity of melanoma cell lines from patients to autologous T cell-mediated cytotoxicity." (PMID 30510968, 2018). "We treated A375 melanoma xenograft mice with the DNA-damaging topoisomerase I (Top1) inhibitor CPT11 (irinotecan), the poly(ADP-ribose) polymerase (PARP) inhibitor olaparib, or a combination of both drugs." (PMID 28158293, 2017). "The topoisomerase I (TOP1) gene is located at 20q12, a region that frequently undergoes copy-number alterations across cancer types, including melanoma, breast, colorectal, ovarian, and gastric cancer." (PMID 24400218, 2013). "In this regard, our results of animal studies revealed that CPT treatment (1 mg/kg body weight) significantly reduced WRN‐depleted melanoma, as compared to WRN‐proficient melanoma, indicating translational potential of TOP1 inhibitor therapy for cancer patients with WRN deficiency." (PMID 35582959, 2022). "Notably, TOP1 inhibitors increase the sensitivity of patient-derived melanoma cell lines to T-cell-mediated cytotoxicity." (PMID 32075966, 2020). "Similar over-expression of Top1 protein have been reported in urinary bladder carcinomas (77%), gastric carcinomas (68%), testicular tumors, renal cell carcinomas (36–100%), malignant melanomas (42%), squamous cell carcinomas (92%), and sarcomas (13%)." (PMID 24400218, 2013). "Amplification of the TOP1 gene has also been reported in melanoma and gastric cancer." (PMID 23577133, 2013). "To further support the role of STING in TOP1 poison-induced immune gene expression, we determined immune gene activation by LMP776 and CPT in a different cell model, the murine melanoma B16 cell line, by using STING gene wild-type (wt) or CRISPR-KO B16 cell lines." (PMID 35794238, 2022).
ovarian carcinoma (16 papers, 2013 to 2025). A malignant neoplasm originating from the surface ovarian epithelium. "This study revealed that TOP1 expression is associated with a poor prognosis and with tumor progression in ovarian cancers." (PMID 26207989, 2015). "TOP1 was associated with poor prognosis in ovarian cancers (p = 0.024)." (PMID 26207989, 2015). "Furthermore, χ2 analysis between the TOP1 levels and clinicopathological characteristics of patients showed that TOP1 overexpression in ovarian cancer was associated with the International Federation of Gynecologists and Obstetricians (FIGO) stage (p < 0.044)." (PMID 26207989, 2015). "In support of this, IHC analyses demonstrated that Top1 protein is primarily associated with tumor cells and much less to normal infiltrating cells and increased Top1 protein expression was found in 43% of ovarian carcinomas." (PMID 24400218, 2013). "We determined whether TOP1 expression in ovarian cancer was associated with poor survival." (PMID 26207989, 2015). "We show that in breast and ovarian cancer patients, high SYCP2 expression is associated with poor prognosis and resistance to an antibody-conjugated TOP1 inhibitor and platinum, respectively." (PMID 38383600, 2024). "Top1 activity is robust in malignant cells and correlates with disease progression in colorectal and ovarian cancers, making CPT a potent agent for anticancer chemotherapy." (PMID 36675143, 2023). "We next investigated the relationship between TOP1 expression levels and the overall survival (OS), defined as patients with a ovarian cancer can die directly from this disease or from an unrelated cause." (PMID 26207989, 2015). "The OS analysis revealed that high TOP1 mRNA expression indicated poor survival of ovarian cancer patients (hazard ratio (HR): 1.28, p = 0.00062)." (PMID 26207989, 2015). "In conclusion, this study demonstrates that DNA topoisomerase I is a reliable marker for ovarian cancer prognosis." (PMID 26207989, 2015). "Notch pathway and DNA topoisomerase I (TOP1) inhibitors have been widely used in cisplatin-resistant ovarian cancers." (PMID 26207989, 2015). "Surprisingly, we discovered that induced persistent upregulation of MYC in TNBC and ovarian cancer cells is associated with sensitivity to TOP1 inhibitors but not TOP2 inhibitors." (PMID 35844787, 2022). "Establishing the role of TOP1 expression in ovarian cancer may facilitate the development of more effective therapeutic strategies." (PMID 26207989, 2015). "In TCGA, ovarian cancer patient samples showed alterations in the gene for topoisomerase I, TOP1." (PMID 25884494, 2015). "TOP1 inhibitors are widely used in treating conventional therapy-resistant ovarian cancers." (PMID 26207989, 2015). "In previous studies designed to investigate the cell response to a novel Top1 poison, ST1968, we noticed that the susceptibility of human SCC and ovarian cancer cells to an early and significant CPT-induced apoptosis was associated with a marked reduction of the PLK1 protein." (PMID 25826089, 2015). "Lee et.al revealed that the overexpression of TOP1 in EOC was correlated to the International Federation of Gynecologists and Obstetricians (FIGO) stages and was associated with advanced stage, which might reflect a high progressive growth of ovarian cancer." (PMID 27315793, 2016). "In this study, we examined the mechanisms associated with the development of camptothecin (CPT) resistance in ovarian cancers and identified evodiamine (EVO), a natural product with TOP1 inhibiting activity that overcomes the resistance." (PMID 26207989, 2015). "Effects of drugs targeting TOP1 for prognosis and therapy in CPT-resistant ovarian cancer are anticipated." (PMID 26207989, 2015). "In breast and ovarian cancer cell lines, high SYCP2 expression correlated with resistance to Cisplatin, a DNA crosslinking agent, and Camptothecin 11 (CPT11, irinotecan), an inhibitor of TOP1." (PMID 38383600, 2024).
ovarian carcinoma (continued). "The wide-scale prevalence of preclinical models exemplifying PARP inhibitors that show clinical activity in ovarian cancer, breast and prostate cancer as single agents, sensitize tumor cells to Top1 poisons in vitro and in vivo propelled combining PARP inhibitors with Top1 poison in the clinics." (PMID 33981998, 2021). "We knocked down EMSY in OVCAR3, an ovarian cancer cell line with EMSY amplification, and measured RAD51 foci formation upon treatment with camptothecin (CPT), an inhibitor that targets DNA topoisomerase I resulting in collapse of the replication fork and DNA double-strand breaks." (PMID 28099152, 2017). "We also searched the mutation status of TOP1 gene in the Cancer Cell Line Encyclopedia (CCLE) and found no alterations of TOP1 in 51 ovarian cancer cell lines, but identified 29 mutations among over 1000 cancer cell lines in that dataset." (PMID 25884494, 2015). "In poorly differentiated ovarian carcinomas the activity of Top1 was found to be much higher than in non-cancerous tissue or benign tumors." (PMID 24400218, 2013). "However, some other studies found that no obvious correlation was observed between the TOP1 expression and the staging and grading of ovarian cancer." (PMID 27315793, 2016).
small cell lung carcinoma (15 papers, 1995 to 2025). Small cell lung cancer (SCLC) is a highly aggressive malignant neoplasm, accounting for 10-15% of lung cancer cases, characterized byrapid growth, and early metastasis. "Topotecan (Tpc) is a topoisomerase 1 (TOP1) inhibitor from the camptothecin group and can be used in clinical practice for the treatment of cervical, ovarian cancer, colon cancer, and small cell lung cancer." (PMID 41155491, 2025). "Topotecan, which is approved for cervical, ovarian, and small-cell lung cancers, acts as both a DNA topoisomerase I inhibitor and a HIF1α inhibitor." (PMID 38893207, 2024). "TPT, a FDA-approved topoisomerase 1 (TOP1) inhibitor, has been used in the treatment of small cell lung cancer." (PMID 36701392, 2023). "Topotecan, a TOP1 inhibitor, is currently used in cancer therapies to treat ovarian, colorectal, pancreatic, and small-cell lung cancer." (PMID 35844787, 2022). "A study on small cell lung cancer (SCLC) cell lines found that TDP1/TOP1 protein ratio is a better predictor than the individual TDP1 or TOP1 protein level, showing good correlation with irinotecan sensitivity in eight out of ten cell lines examined." (PMID 31547492, 2019). "Previous studies have demonstrated that CKD-602, a TOP1 inhibitor, is effective in the treatment of various cancers such as small cell lung carcinoma, oral squamous cell carcinoma and glioblastoma." (PMID 31138113, 2019). "In addition, the application of TDP1 inhibitors has been explored in tumor resistant to TOP1 inhibitors, such as metastatic ovarian, cervical, and small-cell lung cancers." (PMID 40133672, 2025). "Inhibition of ATR and TOP1 is reported to augment the immunogenicity of small-cell lung cancer." (PMID 40282196, 2025). "In Small Cell Lung Cancer (SCLC) cell lines, only cells expressing STING and cGAS respond to a combination of Top1 poisons and PARP inhibitors with increased mRNA levels of Interferon-B gene." (PMID 36114513, 2022).
leukemia (12 papers, 1992 to 2024). A malignant (clonal) hematologic disorder, involving hematopoietic stem cells and characterized by the presence of primitive or atypical myeloid or lymphoid cells in the bone marrow and the blood. "Similar to AraC, GEM inhibited the re-ligation step of Top1 catalysis and Top1-deficient P388 CPT-resistant murine leukemia cells were cross-resistant to GEM, consistent with the in vivo significance of Top1cc for anti-tumor activity." (PMID 31930190, 2019). "Data from previous work by our group showed that CNN1 reduced TOP1 expression levels in both leukemia cell lines." (PMID 35897681, 2022). "It has also been shown that octadecanoic acid has antitumor activity in mouse models and is selectively cytotoxic for MOLT‐4 leukemia cancer cells due to its interaction with DNA topoisomerase I and its ability to induce apoptosis." (PMID 34262737, 2021). "We next compared the effect of the topoisomerase I (TOP1) inhibitor camptothecin (CPT) on ATAC-seq patterns in human leukemia CCRF-CEM (SLFN11-positive) cells and their isogenic SFLN11-knockout." (PMID 32321568, 2020). "Human lymphoma and leukemia cell lines exposed to 3d and Top1, HDAC, and dual Top1/HDAC inhibitor CY700." (PMID 30300374, 2018). "Carbenolide induced apoptosis in K562 leukemia cells by inhibiting DNA topoisomerase I and II (IC50 30 ng/mL) and increased lifespan in mice implanted with P388 leukemia cells." (PMID 34198841, 2021).
lung carcinoma (10 papers, 2015 to 2025). "As targeting ETV4 directly is challenging, our findings present an exciting alternative strategy to exploit TOP1 as novel targets in ETV4‐dysregulated lung cancers." (PMID 40548893, 2025). "Future work should further investigate the benefit of TOP1 and other inhibitors in treating lung cancer addicted to ETV4‐overexpressed transcription and replication across panels of cell lines, patient‐derived organoids, and in vivo experimental test." (PMID 40548893, 2025). "As directly targeting ETV4 is challenging, our findings present an exciting alternative strategy to exploit TOP1 as novel targets in ETV4‐dysregulated lung cancers." (PMID 40548893, 2025). "Topoisomerase 1 (TOP1) poisons are effective antitumor drugs with good efficacy against lung cancers." (PMID 35794238, 2022). "For example, it is known that inhibition of topoisomerase 1 (TOP1) leads to an increase in the formation of readthrough transcripts, while TOP1 inhibitors, irinotecan and topotecan, are widely used in the treatment of colorectal, pancreatic, ovarian, and lung cancers." (PMID 41155268, 2025). "Similarly, the expression of downstream molecular targets such as TOP1, which is highly expressed across several tumor types including breast and lung cancers, may provide additional insight into therapeutic outcomes." (PMID 41425250, 2025).
gastric cancer (8 papers, 2013 to 2022). A primary or metastatic malignant neoplasm involving the stomach. "We investigated antitumor activity and underlying mechanisms of DNA topoisomerase I (TopI) inhibitor gimatecan and irinotecan in gastric cancer (GC) in vitro cell lines and in vivo patient-derived xenograft (PDX) models." (PMID 29237470, 2017). "Trastuzumab deruxtecan, using a novel DNA topoisomerase I inhibitor, can overcome T-DM1 resistance caused by aberrant expression of ATP-binding cassette (ABC) transporters in HER2-positive gastric cancer." (PMID 36348391, 2022). "In gastric cancer, several amplicons have been observed on 20q, including one encompassing the TOP1 gene." (PMID 24400218, 2013).
neuroblastoma (8 papers, 1996 to 2023). Neuroblastoma (NB) is the most common solid, extracranial childhood tumor. "Overall, our mouse studies suggest that combinations of CX-5461 with TOP1 inhibitors are synergistic in vivo and have clinical potential in neuroblastoma." (PMID 34753908, 2021). "CPT-11 (irinotecan) is a DNA-topoisomerase I inhibitor with preclinical activity against neuroblastoma (NB) xenografts." (PMID 15292932, 2004). "Non-high-risk neuroblastomas were marked by footprints of chromosome mis-segregation and TOP1 mutational activity." (PMID 37868040, 2023).
prostate carcinoma (8 papers, 2015 to 2026). A carcinoma that arises from epithelial cells of the prostate gland. "Genes associated with ETV4-fusion-positive prostate cancers were used as the input, and four therapeutic candidate targets, PARP1, NQO1, HSPA5, and TOP1, and the respective selective drugs, olaparib, amrubicin, fluorouracil, and irinotecan, were identified." (PMID 36289913, 2022). "PARP1, NQO1, HSPA5, and TOP1 were identified as potential molecular targets for ETV4-fusion-positive prostate cancer, and olaparib, amrubicin, fluorouracil, and irinotecan were suggested as candidate drugs, respectively." (PMID 36289913, 2022). "Indeed, ER- and androgen receptor (AR)-induced transcription in breast and prostate cancer involves transient DSBs generated by TOP1 and TOP2." (PMID 26411678, 2015). "For example, AR, EGFR, DDR2 and MAP2K2 were connected with mtDNA genes in prostate cancer, and TMPRSS2, NF1, PIK3CA, BRCA1 and TOP1 were the top neighbors of mtDNA genes in multiple cancer types." (PMID 32024997, 2020).
viral infection (8 papers, 2011 to 2025). "Evidence that TOP1 is directly active on the viral genome includes observations that CPT cannot effectively inhibit viral infection after TOP1 knockdown and that there is an increased colocalization of TOP1 with viral DNA after CPT treatment." (PMID 40874743, 2025). "Considering these mechanistic differences, it is possible that inhibition of viral infection with β-Lapachone results from modulation of various other cellular pathways in addition to TOP1 inhibition." (PMID 40874743, 2025). "Consistently, TOP1 inhibition regulates the production of pro-inflammatory cytokines and chemokines during viral infection." (PMID 39156107, 2024). "Recent studies by the Marazzi group have reported that TOP1 inhibition protects against cell death induced by SARS-CoV-2 infection and suggested that TOP1 contributes to viral infection-induced pro-inflammatory responses." (PMID 39156107, 2024). "Thus, inhibition of viral infection by CPT is consistent with TOP1 catalytic activity playing a role in HSV-1 infection." (PMID 40874743, 2025). "We observed DNA laddering patterns for H. ericina and P. pouchetii cultures upon treatment with camptothecin, a DNA topoisomerase I inhibitor known to induce replication arrest and PCD, thereby confirming the inducible PCD-like DNA fragmentation phenotype associated with virus infection." (PMID 25013242, 2014). "Taken together, these data demonstrate that CPT acts through TOP1 inhibition to restrict viral infection, and at higher concentrations, there may be non-specific effects of CPT on viral yield." (PMID 40874743, 2025). "We next carried out siRNA knockdown of TOP1, as well as topoisomerase 2 (TOP2), to assess whether depletion of either topoisomerase mimics the antiviral effects of CPT or alters the compound’s efficacy in suppressing viral infection." (PMID 40874743, 2025).